FXYD3 (FXYD domain containing ion transport regulator 3)
Diseases named in the same sentence as FXYD3 in open-access papers (continued):
Sharing a sentence is not in itself a finding about the gene and the disease.
colon cancer (5 papers, 2015 to 2023). "Chemoresistance in colon cancer has also been linked with FXYD3, an ion transport regulator and target of miRNA-143, and an association has been shown with progression free survival." (PMID 31979312, 2020). "Strikingly, FXYD3 is transcriptionally activated by 5-fluorouracil treatment in the colon cancer cell line H630." (PMID 26392389, 2015). "Strong FXYD3 expression was observed in the infiltrative type in gastric and colon cancer." (PMID 35892856, 2022). "The expression of FXYD2, FXYD3 and FXYD4 is an independent prognostic factor for for the survival of colon cancer." (PMID 34753441, 2021).
endometrial cancer (5 papers, 2014 to 2023). Primary or metastatic malignant neoplasm involving the endometrium (mucous membrane that lines the endometrial cavity). "The correlation between endometrial cancer risk factors, clinicopathological features and FXYD3 expression is analyzed and discussed." (PMID 25013464, 2014). "FXYD3 has been linked to overexpression in many cancer types and correlated with fertility frequency, thereby linking the high concordance of this gene with breast and endometrial cancers." (PMID 36598637, 2023). "In the present study, immunohistochemistry was used to detect the differential FXYD3 expression and corresponding pathological changes in endometrial tissue samples obtained from patients diagnosed with endometrial cancer." (PMID 25013464, 2014). "FXYD3 expression was examined in the normal endometrium samples (n=21), the atypical endometrial hyperplasia samples (n=18) and the endometrial cancer tissue samples from surgically removed specimens (n=50)." (PMID 25013464, 2014). "The percentage of FXYD3-positive cell expression in the normal endometrium, atypical hyperplasia and endometrial cancer tissues samples was 0, 22, and 26%, respectively." (PMID 25013464, 2014). "The percentage of FXYD3-positive cells in the normal endometrium, atypical endometrial hyperplasia and endometrial cancer tissue samples was 0, 22 and 26%, respectively." (PMID 25013464, 2014). "Our results show that FXYD3 expression in endometrial cancer tissues is correlated with fertility frequency (P=0.024)." (PMID 25013464, 2014). "The percentage of FXYD3-positive cells in the normal endometrium, endometrial hyperplasia and endometrial cancer tissue samples was 0, 22, and 26%, respectively." (PMID 25013464, 2014). "The present study investigated the correlation between FXYD3 expression and endometrial cancer using immunohistochemical analyses of normal endometrium, atypical hyperplasia and endometrial cancer tissue samples." (PMID 25013464, 2014). "The percentage of FXYD3-positive cells in the atypical hyperplasia and endometrial cancer tissues were significantly increased when compared with samples in the normal endometrium group (P=0.007 and P=0.037, respectively)." (PMID 25013464, 2014). "FXYD3 expression in the endometrial carcinoma group was negatively correlated with fertility frequency." (PMID 25013464, 2014). "From these study results, we propose that FXYD3 may be a promising biomarker for endometrial cancer." (PMID 25013464, 2014). "Among the 50 endometrial cancer tissue samples, 13 exhibited FXYD3-positive cells." (PMID 25013464, 2014). "FXYD3 expression was analyzed by streptavidin-peroxidase immunohistochemistry in 21 normal endometrial tissue samples, 18 atypical endometrial hyperplasia samples and 50 tissues obtained from patients diagnosed with endometrial cancer." (PMID 25013464, 2014). "In conclusion, FXYD3 is a potential biomarker for endometrial cancer, and its upregulation may be an early event in endometrial carcinoma progression." (PMID 25013464, 2014). "In addition, FXYD3 expression in endometrial carcinoma correlates with fertility frequency." (PMID 25013464, 2014).
bladder cancer (2 papers, 2016 to 2024). "FXYD3 shows a 3.3 average fold increase expression in bladder cancer." (PMID 27716384, 2016).
cervical cancer (2 papers, 2020 to 2021). A primary or metastatic malignant neoplasm involving the cervix. "In cervical cancer, FXYD3 was confirmed to interact with the LINC01503/miR-342-3p/FXYD3 axis, providing promising therapeutic targets." (PMID 34270462, 2021).
gastric cancer (2 papers, 2022). A primary or metastatic malignant neoplasm involving the stomach. "Specifically, 8 genes (NRP1, MNX1AS1, SSRP1, PRDX2, PLRG1, LGALS4, SNX5 and FXYD3) were found to be highly expressed in stomach cancer tissues compared to normal tissues." (PMID 35831348, 2022). "Validation of the RIPK genes through GEPIA identified 8 genes (NRP1, MNX1, SSRP1, PRDX2, PLRG1, LGALS4, SNX5 and FXYD3) which are highly expressed in stomach cancer were significantly down-regulated in PRU treated samples." (PMID 35831348, 2022). "Specifically, 8 genes NRP1, MNX1, SSRP1, PRDX2, PLRG1, LGALS4, SNX5 and FXYD3) which are highly expressed in stomach cancer were significantly down-regulated in PRU treated samples." (PMID 35831348, 2022). "Gene expression profiling using oligonucleotide arrays on 22 gastric cancer tissues revealed an increase in the expression of the genes LGALS4, FXYD3, SSRP1, and PRDX2 (Reference: GSE2685)." (PMID 35831348, 2022).
glioma (2 papers, 2014 to 2022). A benign or malignant brain and spinal cord tumor that arises from glial cells (astrocytes, oligodendrocytes, ependymal cells). "Increases in FXYD3 expression are higher in females than in males and in multiple site gliomas than in single sites." (PMID 25018677, 2014).
prostate carcinoma (2 papers, 2007 to 2014). A carcinoma that arises from epithelial cells of the prostate gland. "In the same study, the suppression of FXYD3 expression caused a significant decrease in the cellular proliferation of prostate cancer cell lines." (PMID 25013464, 2014). "It has also been reported that FXYD3 expression is downregulated in specific prostate cancer cells." (PMID 25013464, 2014).
atherosclerosis (1 paper, 2022). A disease characterized by the build-up of fatty material and calcium deposition in the arterial wall resulting in partial or complete occlusion of the arterial lumen. "In the process of atherosclerosis, the expression of FXYD3 gene was significantly down-regulated, while the expression of FXYD6 was upregulated." (PMID 35651949, 2022).
breast tumours (1 paper, 2025). "FXYD3 was first identified as an overexpressed protein in murine breast tumours initiated by oncogenic ras and neu mutations, and was found to induce chloride conductance in Xenopus oocytes." (PMID 39783776, 2025).
cholangiocarcinoma (1 paper, 2026). A carcinoma that arises from the intrahepatic biliary tree (intrahepatic cholangiocarcinoma) or from the junction, or adjacent to the junction, of the right and left hepatic ducts (hilar cholangiocarcinoma). "The findings revealed markedly elevated surface expression of FXYD3 in cholangiocarcinoma cells compared to that in normal cholangiocytes." (PMID 41164952, 2026). "We investigated the expression levels of FXYD3 in normal cholangiocytes (HIBEC) and cholangiocarcinoma cell lines (RBE, HCCC‐9810, HUCCT1, QBC939, and HUH28)." (PMID 41164952, 2026).
clear renal cell carcinoma (1 paper, 2022). "Nevertheless, the prognostic value of FXYD3 expression has been undiscovered in clear renal cell carcinoma (KIRC)." (PMID 35892856, 2022). "However, the prognostic value of FXYD3 expression in clear renal cell carcinoma (KIRC) is unclear." (PMID 35892856, 2022).
colon adenocarcinoma (1 paper, 2022). "Consistent with this, FXYD3 knockdown impairs growth and disperses cells in MCF-7 tumors expressed in mice, and in human colon adenocarcinoma Caco-2 cells, FXYD3 knockdown decreases the transepithelial electrical resistance of confluent cell layers consistent with decreased intercellular adhesion." (PMID 35371992, 2022).
esophageal carcinoma (1 paper, 2021). A primary or metastatic malignant neoplasm involving the esophagus. "Research showed that high expression of FXYD3 in esophageal carcinoma promoted tumor progression, resulted in an unfavorable prognosis." (PMID 34270462, 2021).
heart failure (1 paper, 2025). Inability of the heart to pump blood at an adequate rate to meet tissue metabolic requirements. "Several members of the FXYD family have been linked to major human diseases, including heart failure (FXYD1), hypomagnesemia (FXYD2), cancer (FXYD3, FXYD5), and schizophrenia (FXYD6), making them attractive specific targets for future therapies." (PMID 40428357, 2025).
lymph node metastases (1 paper, 2021). "This overexpression was thought to be correlated with tumor stage and lymph node metastases, and high expression of FXYD3 tended to result in an increased incidence of distant metastasis after patients underwent preoperative radiotherapy for rectal cancer." (PMID 34270462, 2021).
metastatic tumor (1 paper, 2023). "The three potential targets FXYD3, ALPP, and TSPAN15 were further explored regarding their expression profile in non-tumoral (normal), primary site tumor, and metastatic tumor tissues, using GeneChip data from TNMplot database." (PMID 37047289, 2023).
non-small cell lung carcinoma (1 paper, 2014). A group of at least three distinct histological types of lung cancer, including non-small cell squamous cell carcinoma, adenocarcinoma, and large cell carcinoma. "In non-small cell lung cancer, FXYD3 expression in tumors for patients with poor prognoses is higher than in those with better prognoses." (PMID 25013464, 2014).
ovarian carcinoma (1 paper, 2023). A malignant neoplasm originating from the surface ovarian epithelium. "Thus, FXYD3 and ALPP could be used as biomarkers for primary sites of ovarian tumors and TSPAN15 as a biomarker for ovarian cancer metastasis." (PMID 37047289, 2023).
pancreatic ductal adenocarcinoma (1 paper, 2025). An infiltrating adenocarcinoma that arises from the epithelial cells of the pancreas. "FXYD3 is a Na/K‐ATPase modulator which is upregulated in pancreatic ductal adenocarcinoma (PDAC), but its prognostic role is unknown." (PMID 39783776, 2025).
rectal cancer (1 paper, 2021). A primary or metastatic malignant neoplasm that affects the rectum. "High expression of FXYD3 increased incidence of distant metastasis after undergoing preoperative radiotherapy (RT) in patients with rectal cancer." (PMID 34270462, 2021).
type 2 diabetes (1 paper, 2014). "Because this epigenetic regulation is reversed in glucose-unresponsive islets from diabetic mice and humans, which express higher levels of Fxyd3, loss of imprinting of this locus may contribute to beta-cell dysfunction characteristic of type 2 diabetes." (PMID 25058609, 2014). "Finally, to determine whether Fxyd3 was also expressed in human islets and whether its expression was regulated in type 2 diabetes, we assessed Fxyd3 expression by microarray and qRT-PCR analysis." (PMID 25058609, 2014).
undifferentiated carcinoma (1 paper, 2015). A usually aggressive malignant epithelial neoplasm composed of atypical cells which do not display evidence of glandular, squamous, or transitional cell differentiation. "Of the 32 tumors with FXYD3 weak staining, there were two tumors that were classified as undifferentiated carcinoma, whereas there was no tumor with this classification in the 211 tumors with strong staining." (PMID 26392389, 2015).
cancer (35 papers, 2011 to 2026). A tumor composed of atypical neoplastic, often pleomorphic cells that invade other tissues. "Further experiments are necessary to unravel the molecular mechanisms underlying this phenomenon, as FXYD3 remains a promising target for cancer therapy to improve treatment outcomes." (PMID 37966117, 2023). "Although increased expression of FXYD3 is associated with various cancers, the relevant biological factors and their associated mechanisms of actions through which FXYD3 is increased in transforming and cancer cell systems have not been identified." (PMID 26090296, 2015). "Our findings highlight the role of FXYD3 in cancer‐related inflammation and innate immune signaling, thereby providing a new paradigm for understanding the pathogenesis of ICC." (PMID 41164952, 2026). "Given the relationship between FXYD3 and the Na/K‐ATPase, there are numerous plausible mechanisms to explain the potential role of FXYD3 in cancer progression." (PMID 39783776, 2025). "One of the FXYD proteins, FXYD3, confers chemotherapy resistance when it is overexpressed in cancer cells." (PMID 39769162, 2024). "Cells positive for NRP1 (NRP1med and NRP1hi cells) or IGF1R (IGF1Rmed and IGF1Rhi cells) and cells positive for FXYD3 (FXYD3med and FXYD3hi cells) were more abundant among P3 patient-derived cancer cells than in P6 and P1 patient-derived cells, respectively." (PMID 37966117, 2023). "FXYD3 which is considered as an ion transport regulator is reported to be up- or down-regulated in different types of cancer." (PMID 37535601, 2023). "FXYD3 expression is upregulated in bulk cancer cells such as those in breast, pancreas, colon, prostate, and endometrium." (PMID 37966117, 2023). "FXYD3 is often highly expressed in cancers, particularly in those of the pancreas, prostate, and breast." (PMID 35371992, 2022). "The FXYD3 peptide derivatives we report here are useful tools for exploring the role of overexpressed FXYD3 in cancer and its potential as a treatment target." (PMID 35371992, 2022). "We are not aware of studies reporting overexpression of the intact α/β/FXYD3 Na+/K+-ATPase molecular complexes in the intracellular compartment in cancers." (PMID 35371992, 2022). "FXYD3 is also known as mammary tumor marker 8 (Mat-8), and cell proliferation is considered as a plausible role of FXYD3 in cancer." (PMID 34262595, 2021). "Of note, the clinical significance of FXYD domain‐containing ion transport regulator 3 (FXYD3), a sodium‐potassium ATPase regulator, has been demonstrated in several types of cancer." (PMID 33350586, 2021). "Accordingly, FXYD3, being a sodium‐potassium ATPase regulator, has been confirmed as a key mediator in a large number of cancer types." (PMID 33350586, 2021). "CTD-2527I21.15 locates adjacently to FXYD3 in chromosome 19 and potentially cis-regulates its expression in cancer." (PMID 30453959, 2018). "Two family members, FXYD3 (mammary tumor protein 8 kD) and FXYD5 (dyshaderin or resembles ion channel), are highly expressed in numerous malignant tumors and are associated with tumor cell invasion and migration, involvement of lymph nodes and prognosis." (PMID 24396454, 2014). "We found that knockdown of FXYD3 led to a marked decrease in cancer cell proliferation." (PMID 37966117, 2023). "Cancer cells were sorted using anti-FXYD3 and anti-NRP1 or anti-IGF1R antibodies." (PMID 37966117, 2023). "This indicates that FXYD3 is essential for the proliferation of cancer cells and may play a critical role not only in the maintenance of ancestor-like CSCs but also in the proliferation of differentiated cancer cells." (PMID 37966117, 2023). "One of the FXYD proteins, FXYD3, confers treatment resistance when overexpressed in cancer cells." (PMID 35371992, 2022). "Accumulating evidence suggests the biological role of FXYD3 in multiple cancers." (PMID 35892856, 2022).
cancer (continued). "Facilitated by bonds from FXYD proteins to α and β subunits seen in the crystal structure, the primary overexpression of FXYD3 in cancer cells might lead to an intracellular accumulation of FXYD3/α/β Na+/K+-ATPase complexes." (PMID 35371992, 2022). "Similarly, FXYD3 is noted to show overexpression in carcinoma cells with extensive role in the cytoplasm during the tumorigenesis development." (PMID 35831348, 2022). "In several cancer types expression of FXYD3 appears to be deregulated." (PMID 26392389, 2015). "As such, FXYD3 is being scrutinized as a potential novel biomarker for cancer." (PMID 25013464, 2014). "FXYD3 expression is upregulated in numerous cancer cell types." (PMID 25013464, 2014). "Moreover, FXYD3 has also been implied to be correlated with the prognosis of these cancers." (PMID 32432654, 2020). "FXYD3, an FXYD‐domain‐containing regulator in the Na+/K+ ATPase family, is overexpressed in several common cancers." (PMID 41164952, 2026). "Differential gene expression and gene ranking analyses revealed that the expression of CD74, HLA-DRA, HLA-DRB1, and FXYD3 was elevated in MHC-II+ cancer cells, whereas the expression of LOXL2 and DLL4 was increased in MHC-II− cancer cells." (PMID 41281745, 2025). "We observed that the cells double-positive for NRP1 and FXYD3 (ancestor-like CSC enriched) were increased by paclitaxel treatment and they were significantly diminished by combined treatment with ouabain in cancer tissues." (PMID 37966117, 2023). "The mRNA expression level of FXYD3, LGALS4, USH1C, ECI2, TGM2, and HMGA2 genes which are involved in EMT, drug resistance, and cancer progression were measured in HCT116/OX-R4.3 and HCT116/OX-R10 cells by qRT-PCR." (PMID 37535601, 2023). "FXYD1, FXYD3, FXYD6 and FXYD7 were significantly downregulated in cancer samples, while FXYD4 and FXYD5 were markedly overexpressed." (PMID 34270462, 2021). "Meanwhile, members of theFXYD protein family such as FXYD3 and FXYD5 play an important role in the pathogenesisof numerous malignant tumors and are used as indicators for the biologicalcharacteristics and prognostic factors of certain tumors." (PMID 33817214, 2020). "The roles of FXYD3 (Mat-8) and FXYD5 (dysadherin) are unclear, but they appear to be overexpressed in some cancer cells, and FXYD6 and 7 are expressed in the brain." (PMID 28634454, 2017). "MAT8 also named FXYD-3, is a chloride channel or chloride channel regulator and acts as a prognostic factor for cancers." (PMID 24295240, 2013). "FXYD3 was expressed in human pancreatic tissues, with a significant upregulation in at least 50% of PDAC tissues, due mainly to increased expression levels within the cancer cells themselves." (PMID 38184732, 2024). "In addition, the PI3K/AKT pathway-related genes including FXYD3, SMAD7, and ITGB8, are involved in stem cell-like properties in various cancer types, which are transcriptionally regulated by SETD541–47." (PMID 37963940, 2023). "Fxyd3 is a member of the FXYD family of proteins known to regulate ion transporting membrane proteins, which can modulate cellular differentiation, and whose expression is strongly up-regulated in some tumors, making it a good cancer biomarker." (PMID 25058609, 2014). "FXYD3-pep SKSK alone at 1 or 2 μM did not decrease cancer cell viability (data not shown)." (PMID 35371992, 2022). "Thus, FXYD3 and ATP1B1 may cooperatively maintain the activity of the Na+/K+ pump and, consequently, support drug resistance in ancestor-like CSCs while working independently in other cancer cells for other functions." (PMID 37966117, 2023).